MIR649 (microRNA 649)
Synonyms: hsa-mir-649; MIRN649
Gene: MicroRNA gene on chromosome 22 (21,034,176 to 21,034,272, reverse strand). Ensembl gene ENSG00000207575.
Gene Ontology:
Biological process: miRNA-mediated post-transcriptional gene silencing
Homologues: Orthologues: chimpanzee ptr-mir-649 (97% identical).